AR (androgen receptor)
Diseases named in the same sentence as AR in open-access papers (continued):
Sharing a sentence is not in itself a finding about the gene and the disease.
prostate carcinoma (continued). "The KLK3 (PSA) promoter is used extensively by the prostate cancer field to measure AR-dependent transcription." (PMID 33976187, 2021). "We observed that inhibition of KIF4A expression reduced clonogenic survival in both AR-dependent and AR-independent prostate cancer models." (PMID 34326322, 2021). "The KRE and kavalactone weakly inhibited both MAO-A and LSD1 activities in prostate cancer, leading to their inhibitory effect on AR signaling and cell proliferation." (PMID 34368644, 2021). "Through our studies, we have further characterized the mechanism by which PIM1 phosphorylation of AR alters AR transcriptional activity in prostate cancer." (PMID 34697370, 2021). "ADT lowers testosterone levels, which prevents androgen receptor signalling; however, GnRH agonists and antagonists suppress testosterone levels through different mechanisms, which may confer different CV risk as measured by event rates for patients with prostate cancer who receive ADT." (PMID 32979057, 2021). "Another study in prostate cancer cells has identified miR-185-binding sites in the 3′UTR of the AR transcript." (PMID 34831421, 2021). "Very central role in prostate cancer treatment-resistance is the steroid and nuclear receptor, androgen receptor, AR, itself: AR activity and its target genes are either lost or blocked in t-NEPC." (PMID 33572108, 2021). "We found that co-treatment with DIM and ENZ inhibited prostate cancer cell proliferation, invasion and migration through regulating Wnt signaling to reduce the expressions of AR and AR-v7." (PMID 33441906, 2021). "Androgen receptor (AR) signaling inhibitors provide limited survival benefits to patients with prostate cancer (PCa), and worse, few feasible genomic lesions restrict targeted treatment to PCa." (PMID 34315855, 2021). "IL-23-IL-23R-RORγ axis activated the androgen receptor pathway in prostate cancer cells, regulating resistance to ADT." (PMID 34095111, 2021). "SFPQ has been previously shown to regulate the stability of AR transcripts in prostate cancer and neurons and our own analysis of SFPQ-enriched transcripts identify SOX10 and the lncRNA, TMEM51-AS1 as being destabilised in SFPQ depleted cells." (PMID 34218270, 2021). "Prostate cancer is a major disease where AR and its transcription factor function affect a significant number of patients worldwide." (PMID 33634124, 2021). "Sample‐shared AR sites are conserved across disease transition states, which are enriched in genes essential for prostate cancer proliferation." (PMID 33576154, 2021). "For instance, inhibition of CDK9 was recently shown to repress the AR‐driven oncogenic programme in castration‐resistant prostate cancer cells in vitro and in vivo." (PMID 34092037, 2021). "Targeting the androgen receptor (AR) signaling axis has been, over decades, the mainstay of prostate cancer therapy." (PMID 33420371, 2021). "Inhibition of ELK1 reduces expression of AR target genes and suppresses prostate cancer cell growth." (PMID 33513133, 2021). "Androgen receptor (AR) in prostate cancer (PCa) can drive transcriptional repression of multiple genes including MYC, and supraphysiological androgen is effective in some patients." (PMID 34911936, 2021). "Androgen receptor (AR)-mediated transcription is the primary driver of prostate cancer (PCa) growth and proliferation." (PMID 33975627, 2021). "This modification leads to increased transcriptional activity of the receptor and was shown to occur in several prostate cancer cell lines; comparably, deacetylation leads to decreased AR activity." (PMID 34638264, 2021). "The androgen receptor (AR) is one of the main components in the development and progression of prostate cancer (PCa), and treatment strategies are mostly directed toward manipulation of the AR pathway." (PMID 33805919, 2021). "Given the central role of the AR in prostate cancer tumorigenesis, extensive effort has been put into developing activity gene signatures for this factor." (PMID 33525365, 2021).
prostate carcinoma (continued). "The androgen receptor (AR) and AR-related signaling pathways play important roles in the development of prostate cancer." (PMID 34833084, 2021). "It inhibits prostate cancer cells by inhibiting androgen receptor and heat shock protein and shows antitumor activity in docetaxel‐refractory metastatic prostate cancer and breast cancer." (PMID 34496154, 2021). "Overall, the results showed that Jazz90 and Jazz167 function as cytostatic HDAC inhibitors in AR-null prostate cancer cells." (PMID 33572730, 2021). "To date, in human medicine, AR-targeted drugs have been approved for the treatment of prostate cancer, and different AR inhibitors are being investigated for the treatment of HBC, specifically for the LAR subtype of triple-negative breast cancer." (PMID 33681329, 2021). "The primary therapy for prostate cancer (PCa) is targeting androgen receptor (AR) signaling, while the disease inevitably progresses to castration-resistant prostate cancer (CRPC)." (PMID 34315855, 2021). "In prostate cancer, androgen steroid hormones bind to the androgen receptor (AR) and thereby trigger a key lineage-specific, oncogenic transcriptional program." (PMID 33420371, 2021). "Our recent studies have shown that CYP3A5 inhibition can block androgen receptor (AR) signaling, critical for prostate cancer growth." (PMID 34570813, 2021). "In the TCGA cohort, 98% of the primary prostate cancer samples were positive for AR-FL and 29% were positive for AR-V7." (PMID 34168263, 2021). "Androgen regulation of Skp2 was also reported by others in LNCaP and C4-2 cells; however, Skp2 can also promote prostate cancer independently of the androgen receptor." (PMID 33799604, 2021). "The glucocorticoid receptor (GR)-regulated transcriptome highly overlaps with AR gene signatures, and compensatory activation of the GR signaling can lead to enzalutamide resistance in prostate cancer xenograft models." (PMID 33809714, 2021). "The results presented herein demonstrate for the first time that TAD can modulate AR expression in prostate cancer cells in vitro." (PMID 33451122, 2021). "The aim of this study was to assess the antitumoral effects of the combination of hydralazine, a DNA methylation inhibitor, with enzalutamide, an antagonist of the androgen receptor, in prostate cancer cell lines." (PMID 34440180, 2021). "Androgen receptor signaling refers to one critical channel in prostate carcinoma, and cases receive the initial administration with ADT." (PMID 34568317, 2021). "Here, we describe the development and application of a robust ddPCR assay that can efficiently and reproducibly quantify the expression of full length AR (AR-FL), AR-V7, and AR-v567es in CTCs isolated from the peripheral blood of patients with prostate cancer." (PMID 34168263, 2021). "This therapy targets the androgen receptor (AR), a receptor that plays a crucial role both in the physiology of the prostate and pathogenesis of prostate cancer." (PMID 34191854, 2021). "Its signaling in PCa cells is involved in regulating the transcriptional activity of the androgen receptor (AR), and substantiates the transition to an androgen independent proliferation of prostate cancer cells." (PMID 34357036, 2021). "The activation of androgen receptor (AR) signaling plays a critical role in driving the initiation and progression of prostate cancer." (PMID 34392453, 2021). "Even castration resistance prostate cancer remains dependency on AR signaling; therefore, it is highly important to identify potential targets for therapeutic interventions in prostate cancer." (PMID 33219721, 2021). "Hsp27 has previously been reported to facilitate AR nuclear translocation in a p38 mitogen-activated protein kinase (MAPK) dependent manner in castration-sensitive prostate cancer cell lines." (PMID 33671134, 2021).
prostate carcinoma (continued). "Prostate cancer among black men is known to have specific molecular characteristics, especially the androgen receptor (AR) or enzymes related to the androgen metabolism (i.e CYP17)." (PMID 33446131, 2021). "Targeting of the androgen receptor (AR) axis has been the foundation of therapy for advanced prostate cancer for over 75 years." (PMID 34575033, 2021). "This is in line with observations in prostate cancer, which is also highly dependent on AR-signaling for proliferation and progression." (PMID 34298742, 2021). "Targeting KDM4B is thus an alternative therapeutic strategy for advanced prostate cancers driven by c-Myc and AR." (PMID 34335964, 2021). "The key enzyme, stearoyl CoA desaturase (SCD), facilitates proliferation of prostate cancer cells through an AR dependent pathway." (PMID 34822423, 2021). "A recent study presented that miR-206 binds with the androgen receptor and regulate the hormones in both breast and prostate cancer." (PMID 34238129, 2021). "Quercetin demonstrates the capacity to reduce the expression of androgen receptor (AR) in human prostate cancer cell lines, LNCaP, and/or LAPC-4, slowing down cancer progression." (PMID 34685098, 2021). "In the current study we have examined if bergamottin can modulate the growth of the prostate cancer cells by altering AR signaling, prostate specific antigen (PSA) production, and cell cycle blockage." (PMID 34570813, 2021). "Here, we sought to characterize how PIM1 phosphorylation of AR and the AR co-activator, 14-3-3 ζ, alters AR transcriptional activity in prostate cancer." (PMID 34697370, 2021). "Through direct interactions with the Androgen Receptor (AR), FOXA1 helps to shape AR signaling that drives the growth and survival of normal prostate and prostate cancer cells." (PMID 32946061, 2021). "Focussing on prostate cancer, the unique metabolic program driven by the androgen receptor (AR) and the role of this program in fuelling oncogenic growth of prostate cancer are also described." (PMID 34262149, 2021). "Amplification of AR leads to overexpression of AR protein and hypersensitization of prostate cancer cells to residual androgens in patients receiving drug‐induced castration therapy." (PMID 33448107, 2021). "PCAT-1 promotes proliferation through the oncoprotein Myc, while VAV3 regulates AR activity to stimulate growth in prostate cancer." (PMID 33596994, 2021). "Since we observed that bergamottin blocked prostate cancer cell growth, we tested its effect on AR expression and signaling." (PMID 34570813, 2021). "In prostate cancer, ChoKα acts as a chaperone for the androgen receptor (AR), elucidates a feed-forward signalling loop that maintains ChoKα expression and as a consequence reinforces AR signaling activity." (PMID 34070409, 2021). "Our results thus provide proof-of-concept evidence that KDM4B inhibitor can be beneficially used to target both AR and c-Myc driven prostate cancers." (PMID 34335964, 2021). "Inhibition of BRD4 via a BET inhibitor reduces its interaction with AR, inhibits AR transcriptional activity, and reduces prostate cancer cell growth in vitro and in vivo." (PMID 33513133, 2021). "For eight decades, the androgen receptor (AR) has been the primary target for advanced prostate cancer and is thus one of the most studied proteins." (PMID 34439133, 2021). "AR dysfunction is central to prostate cancer (PCa) development and progression and hence the AR serves as a major non-surgical therapeutic target in the disease." (PMID 34075163, 2021). "In prostate cancer, the AR pathway also often remains active in a castration-resistant state, and several studies have shown that AR-dependent resistance mechanisms have evolved." (PMID 34298742, 2021). "Androgen receptor (AR) plays an important role in the malignant progression and metastasis of prostate cancer." (PMID 35342388, 2021).
prostate carcinoma (continued). "MiR-182-5p is another AR-regulated miRNA that facilitates the progression of prostate cancer by targeting the ARRDC3/ITGB4 axis." (PMID 34831421, 2021). "The newest class of medications used exclusively for prostate cancer is the androgen receptor antagonists that inhibit the binding of testosterone and dihydrotestosterone (DHT) with androgen receptors." (PMID 35054441, 2021). "Our finding of KLF5 and AR opposition provides clues to the molecular determinants of KLF5 functioning as an oncogene vs. tumor suppressor in prostate cancer." (PMID 34737261, 2021). "Androgen receptor knockdown in prostate cancer promotes cancer cell migration/invasion via CCL2- dependent STAT3 activation and EMT pathways." (PMID 33986252, 2021). "Prostate cancer (PCa) is a hormone driven cancer, characterised by defects in androgen receptor signalling which drive the disease process." (PMID 35008330, 2021). "FGF11-miR-541 activity in response to T-cell infiltration in prostate cancer contributes to prostate cancer cell invasion, likely through suppression of androgen receptor and matrix metallopeptidase 9 (MMP9) activity." (PMID 34068954, 2021). "Our results confirmed that topoisomerase II catalytic inhibition inhibited proliferation and induced apoptosis of AR-independently growing prostate cancer cells." (PMID 34681904, 2021). "Similar mechanisms for gene overexpression and upregulation of circRNA was described for other genes, e.g., androgen receptor in prostate cancer." (PMID 33603167, 2021). "Combined, our data reveal a core transcriptional program in clonal metastatic prostate cancer, despite epigenomic differences in the AR cistrome." (PMID 33576154, 2021). "In AR-positive prostate cancer cells, RANBP10 formed a protein complex with itself or RANBP9 and then elevated the transcription activity of AR." (PMID 34671019, 2021). "It is conceivable that AR signaling is the most critical factor in prostate cancer development and progression." (PMID 34572596, 2021). "For example, FKBP51 and FKBP52 inhibitors decreased AR-dependent prostate cancer cell proliferation." (PMID 34831344, 2021). "We observed that GHSROS was also able to reciprocally regulate androgen receptor (AR) expression in some prostate cancer cell lines (downregulated upon GHSROS overexpression in PC3 and LNCaP; upregulated upon GHSROS knockdown in DUCaP)." (PMID 33585078, 2021). "The chemical Fulvestrant with a R2 of > 0.9, is used in prostate cancer treatment and is thought to have its action by downregulating the expression of the androgen receptor." (PMID 34165557, 2021). "Understanding the role of the AR signaling pathway in the progression of prostate cancer is important to develop future therapies." (PMID 34685466, 2021). "LINC00844 was demonstrated to be a direct androgen‐regulated target that is actively transcribed in androgen receptor (AR)‐dependent prostate cancer cells." (PMID 34697900, 2021). "Some researchers have also implied the role of androgen receptor in the progression of prostate cancer." (PMID 35201496, 2021). "Our results shed light in the processes controlling prostate cancer progression and make the transient receptor potential melastatin-8 as a ‘druggable’ target in the androgen receptor-expressing prostate cancers." (PMID 34853378, 2021). "Androgen receptor (AR) signaling inhibitors represent the standard treatment in metastatic castration resistance prostate cancer (mCRPC) patients." (PMID 33500577, 2021). "In 2008, the first nutlin-based small molecule PROTAC has been developed to target androgen receptor (AR) for degradation in prostate cancer cells." (PMID 34350175, 2021). "Low-density lipoprotein receptor-related protein-1 and androgen receptor upregulating under hypoxic conditions are involved in prostate cancer." (PMID 34073059, 2021).
prostate carcinoma (continued). "Based on these reports, it appears that spironolactone acts as a partial AR agonist in androgen-depleted environments, such as that in patients treated for prostate cancer." (PMID 34094953, 2021). "Supporting the biological relevance of positive feedback between AR and 6PGD, pharmacological co-targeting of both factors was more effective in suppressing the growth of prostate cancer cells than single-agent therapies." (PMID 34382934, 2021). "In this regard, it seems difficult to study in Drosophila the prostate cancer mechanisms that are directly dependent on androgen receptor signaling." (PMID 34572036, 2021). "ASC-J9® was developed as an AR degradation enhancer, and has shown efficacy in preclinical studies in slowing progression of Enza-resistant prostate cancer." (PMID 34272475, 2021). "Androgen signaling through the androgen receptor (AR) directs gene expression in both normal and prostate cancer cells." (PMID 33976187, 2021). "There have been many advances in prostate cancer treatment that have dramatically improved the outlook for a lot of patients, especially by targeting a key factor in prostate cancer development called the androgen receptor." (PMID 33525365, 2021). "We have shown in the prostate cancer setting that AR binds to intron 5 of EWSR1 to directly upregulate a previously uncharacterized isoform that we have termed ntEWS." (PMID 34409300, 2021). "The main aim of this review is to summarize the effects of interleukins at different stages of prostate cancer with emphasis on interactions with androgens and AR." (PMID 34204596, 2021). "Patients with mCRPC were previously treated with ≥ 2 lines of systemic therapy, including ≥ 1 androgen receptor-axis-targeted therapy for prostate cancer." (PMID 33754187, 2021). "We first surveyed TMPRSS2 and AR expression across a panel of well-characterized prostate cancer cell lines and two previously established organoid lines MSKPCa1 and MSKPCa321." (PMID 33558541, 2021). "Selected antagonists interfere in non-genomic androgen action and abolish the androgen-induced androgen receptor/TRPM8 complex assembly as well as the increase in intracellular calcium levels in prostate cancer cells." (PMID 34853378, 2021). "It has been also suggested that NANOG associates with androgen receptor (AR) and FOXA1 to regulate pro‐differentiation genes and castration resistance in prostate cancer." (PMID 33439550, 2021). "IL-8 is a cytokine expressed in prostate cancer tissue and microenvironment and promotes proliferation and androgen receptor-mediated transcription." (PMID 34204596, 2021). "In vitro and in vivo studies have shown that genetic and pharmacological inhibition of USP14 induces degradation of an androgen receptor (AR), favoring tumor suppression in AR-positive breast cancer cells or prostate cancer cells." (PMID 33928122, 2021). "In AR-positive prostate cancer cells, RANBP10 was highly expressed and was responsible for the activation of AR, thereby contributed to prostate cancer development and progression." (PMID 34671019, 2021). "As we previously reported that PRPF6 enhances transactivation function of AR 25, we then analyzed the impact of PRPF6 on the growth and motility characteristics of AR-positive prostate cancer cells by lentivirus-mediated knockdown of PRPF6." (PMID 33390843, 2021). "This lncRNA is a cytoplasmic lncRNA, which increases proliferation and viability of prostate cancer cells via sustaining AR activity even in androgen-depleted settings." (PMID 34831421, 2021). "This is an interesting finding as in prostate cancer, especially in ﻿castration-resistant prostate cancer, high cytoplasmic DDX3 expression was associated with lower AR expression." (PMID 33974127, 2021). "Promising AR-targeted strategies in clinical trials have been reported in several non-prostatic cancers, such as hepatocellular carcinoma, breast cancer, bladder cancer, and ovarian cancer." (PMID 33947843, 2021).